SFRP2 (secreted frizzled related protein 2)
Diseases named in the same sentence as SFRP2 in open-access papers (continued):
Sharing a sentence is not in itself a finding about the gene and the disease.
dysplasia (3 papers, 2019 to 2026). A usually neoplastic transformation of the cell, associated with altered architectural tissue patterns. "The ENDCAP-C trial, a multicenter study to assess the role of molecular markers in improving the detection of dysplasia, identified the methylation of a five-marker panel (SFRP2, SFRP4, WIF1, APC1A, APC2) that accurately detected ulcerative colitis associated dysplasia." (PMID 41562706, 2026).
endometriosis (3 papers, 2021 to 2025). The growth of functional endometrial tissue in anatomic sites outside the uterine body. "Activation of Wnt signaling by SFRP2 is also observed in endometriosis, in which SFRP2 is highly upregulated compared to normal endometrium." (PMID 33140138, 2021). "The results indicated that the C1 SFRP2+ Fibroblast and C3 RAMP1+ Fibroblast subpopulations predominantly originated from the Endometriosis tissue type, while the C0 FHL2+ Fibroblast and C2 CXCR4+ Fibroblast subpopulations were mostly derived from the Endometriomas tissue type." (PMID 41159025, 2025). "Regarding tissue type preference, the C0 FHL2+ Fibroblast and C2 CXCR4+ Fibroblast subpopulations were more common in Endometriomas, while the C3 RAMP1+ Fibroblast, C1 SFRP2+ Fibroblast, and C4 TFF3+ Fibroblast subpopulations were predominantly found in Endometriosis." (PMID 41159025, 2025).
esophageal cancer (3 papers, 2016 to 2022). A primary or metastatic malignant neoplasm involving the esophagus. "Together, these data indicate that SFRP2 may play a protective role against the progression of esophageal cancer." (PMID 35707047, 2022).
ischemia (3 papers, 2016 to 2023). A hypoperfusion of the BLOOD through an organ or tissue caused by a PATHOLOGIC CONSTRICTION or obstruction of its BLOOD VESSELS, or an absence of BLOOD CIRCULATION. "Inactivation of sFRP2 via a genetic deletion in mice also demonstrated a cardioprotective phenotype, with substantial improvements in cardiac function (EF) in sFRP2 null mice, 14 days after ischemia." (PMID 33494313, 2021). "Some studies have indicated an anti-apoptotic role of Sfrp2 in mediating cellular resistance to UV, TNF, or ischemia-induced apoptosis in mammalian cell lines." (PMID 27048460, 2016).
melasma (3 papers, 2016 to 2024). "sFRP2 has been investigated to be overexpressed in melasma or UV-irradiated skin to stimulate melanogenesis through MITF or tyrosinase upregulation via β-catenin signaling." (PMID 27240341, 2016). "Similarly, ET-1 in SL, HGF in DF /SL, KGF in SL /melasma, IL-1α in SL, sFRP-2 in SL /melasma, and NGF in melasma stimulate melanogenesis of human melanocytes." (PMID 38674144, 2024).
pancreatic adenocarcinoma (3 papers, 2007 to 2017). "SFRP2 hypermethylation had a positive influence on survival of stage I and II pancreatic adenocarcinoma." (PMID 29212200, 2017). "Our study suggests that hypermethylation of SFRP2 has a positive impact on survival in stage I and II pancreatic adenocarcinoma." (PMID 29212200, 2017). "A panel of hypermethylated genes (BMP3, RASSF1A, BNC1, MESTv2, TFPI2, APC, SFRP1 and SFRP2) are able to differentiate between patients with pancreatic adenocarcinoma and a most relevant control group." (PMID 27891190, 2016). "We developed a diagnostic prediction model (age >65, BMP3, RASSF1A, BNC1, MESTv2, TFPI2, APC, SFRP1 and SFRP2), which was able to differentiate between pancreatic adenocarcinoma and a large control group of great clinical relevance." (PMID 27891190, 2016).
ulcerative colitis (3 papers, 2014 to 2025). An inflammatory bowel disease involving the mucosal surface of the large intestine and rectum. "In this study, the methylation and expression status of SFRP2, SFRP4, SFRP5, APC1, and APC2 genes were evaluated for the first time in ulcerative colitis patients in the Turkish population." (PMID 40521787, 2025).
autoimmune myocarditis (2 papers, 2020 to 2021). Autoimmune myocarditis is an autoimmune disease that affects the heart. "sFRP2 attenuated cardiac fibrosis and HF induced by pressure overload and autoimmune myocarditis via the Wnt/β-catenin and TGF-β pathways, respectively." (PMID 34722660, 2021). "Furthermore, in mice with experimental autoimmune myocarditis, SFRP2 inhibited the control of myofibroblast formation and myocardial fibrosis progression by transforming growth factor-β-dependent Wnt secretion." (PMID 32454934, 2020).
brain tumor (2 papers, 2020 to 2022). "The results of the MS‐HRM analysis of all analyzed genes (SFRP1, SFRP2, RUNX3, CBLN4, INA, MGMT, and RASSF1A) showed that their promoter sequence methylation level is significantly higher (P < 0.0001) in DNA samples from brain tumor patients than in the non‐neoplastic brain sample." (PMID 32783304, 2020).
chronic heart failure (2 papers, 2025). "This study was conducted to assess the prognostic value of secreted frizzled-related protein 2 (SFRP2) for mortality and readmission in elderly patients with acute exacerbation of chronic heart failure (HF)." (PMID 40760129, 2025). "Previous studies revealed that a higher level of serum SFRP2 can be considered as an independent predictor of poorer clinical outcomes for elderly patients with acute exacerbation of chronic heart failure." (PMID 41030909, 2025).
colorectal adenocarcinoma (2 papers, 2022 to 2023). The most common type of colorectal carcinoma. "Moreover, expression of the majority of the genes (CACNA1H, COL1A1, COL11A1, FZD8, NGFR, SFRP2, WNT2B, and WNT5A) was associated with the ‘mesenchymal’ CMS group 4 in the TCGA (The Cancer Genome Atlas) Colorectal Adenocarcinoma dataset." (PMID 35892888, 2022). "Similarly, SFRP2, NKX2-3, and ALB were also a part of the machine learning model for the prediction of liver metastasis in colorectal adenocarcinoma." (PMID 37887568, 2023).
colorectal tumors (2 papers, 2014 to 2024). "Given the predominant silencing of SFRP2 observed in colorectal tumors, indicative of its role as a tumor suppressor gene, the rhSFRP2 model provides valuable insights into its impact on pivotal pathways." (PMID 38802858, 2024). "Methylation of the SFRP2, GATA4/5, NDRG4 and VIM promoters in fecal DNA is associated with the presence of colorectal tumors." (PMID 25202404, 2014).
embryonal carcinoma (2 papers, 2010). A non-seminomatous malignant germ cell tumor characterized by the presence of large germ cells with abundant cytoplasm resembling epithelial cells, geographic necrosis, high mitotic activity, and pseudoglandular and pseudopapillary structures formation. "SFRP2 is expressed during retinal development and regulates differentiation in non-neoplastic stem cells in the retina, cardiomyocytes, and the pluripotent mouse embryonal carcinoma stem cell line P19CL6." (PMID 20069066, 2010).
Hypertension (2 papers, 2024 to 2025). The presence of chronic increased pressure in the systemic arterial system. "SFRP2 has been implicated in a range of vascular diseases, including atherosclerosis, hypertension-induced vascular remodeling, and cardiac fibrosis." (PMID 40364828, 2025). "In hypertension-induced vascular remodeling, SFRP2 expression is associated with increased extracellular matrix deposition and vessel wall thickening, potentially exacerbating vascular stiffness and dysfunction." (PMID 40364828, 2025).
liver disease (2 papers, 2013 to 2014). "Therefore, the biological functions of the SNPs in SFRP2 identified in our study may warrant further investigation in studies of liver disease risk and progression." (PMID 24386373, 2013). "This apparent increasing trend might be because promoter methylation mediated silencing of SFRP2 at the early stages of liver disease provides a definitive selective advantage to affected cells and hence helping in their clonal expansion." (PMID 24947038, 2014).
lymph node metastases (2 papers, 2014 to 2019). "Patients with large primary tumor size, advanced TNM stage, and lymph node metastases showed elevated serum sFRP2 concentrations." (PMID 30944668, 2019). "Elevated serum sFRP2 levels are associated with primary tumor size, TNM stage, and lymph node metastases." (PMID 30944668, 2019).
malignant glioma (2 papers, 2014 to 2021). A grade III or grade IV glioma arising from the central nervous system. "Further evidence to support this theory is that SFRP2 has been found to be produced by the majority of malignant glioma cell lines, and SFRP2 overexpressing intracranial glioma xenografts were significantly larger than xenografts consisting of control cells in nude mice." (PMID 24489757, 2014).
non-small cell lung carcinoma (2 papers, 2022 to 2024). A group of at least three distinct histological types of lung cancer, including non-small cell squamous cell carcinoma, adenocarcinoma, and large cell carcinoma. "SFRP2 also regulates non-small-cell lung cancer metastasis via modulation of mitochondrial fission." (PMID 35741755, 2022). "MiR-128-3p plays an important role in promoting the metastasis of non-small cell lung cancer (NSCLC) by downregulating the expression of AXIN1, SFRP2, and WIF1." (PMID 38886806, 2024).
pituitary tumor (2 papers, 2015 to 2023). A benign or malignant neoplasm affecting the pituitary gland. "For example, expression of the Wnt decoy receptors sFRP2, sFRP4, and Wif1 are downregulated in pituitary tumors by epigenetic mechanisms." (PMID 36965619, 2023).
preeclampsia (2 papers, 2023 to 2024). Preeclampsia is a hypertensive disorder of pregnancy that is characterized by new-onset hypertension with proteinuria presenting after 20 weeks of gestation, and depending on mild or severe forms may initially present with severe headache, visual disturbances, and hyperreflexia. "The present study investigates the role of Secreted Frizzled-Related Protein 2 (SFRP2) in trophoblast cells, a key factor in preeclampsia (PE) progression." (PMID 38426532, 2024). "The study of tentative therapeutic methods targeting IL-27/IL-27RA/Wnt or SFRP2 is of great research significance in investigating trophoblast-related diseases, such as FGR, preeclampsia, miscarriage and so on." (PMID 36860682, 2023).
retinoblastoma (2 papers, 2010 to 2021). A malignant tumor that originates in the nuclear layer of the retina. "SFRP2 is an attractive candidate molecule for controlling stem cell proliferation in retinoblastoma tumors in vivo." (PMID 20069066, 2010). "In conclusion, the number of cells with a stem-like phenotype in retinoblastoma cell lines was increased by treatment with LiCl and by reducing the expression of the canonical Wnt pathway inhibitor SFRP2." (PMID 20069066, 2010). "Therefore, SFRP2 is an attractive candidate molecule for mediating stem cell proliferation by LiCl/Wnt signaling in retinoblastoma cell lines." (PMID 20069066, 2010). "Our findings of increased nuclear β-catenin and elevated Wnt ligands in the stem-like cells, and the results from knocking down SFRP2 to activate the Wnt pathway, suggest that Wnt signaling is involved in regulating the number of stem-like cells in the retinoblastoma cell lines." (PMID 20069066, 2010). "To determine whether SFRP2 regulates retinoblastoma stem cells, we experimentally reduced SFRP2 levels, using siRNA, and employed expression of Nanog and Oct3/4 as markers of the stem cell phenotype." (PMID 20069066, 2010). "This together with lack of expression of other well-known RPCs markers such as SOX2, SFRP2, HES1 and HES5, excludes RPCs as cell of origin for retinoblastoma." (PMID 34003213, 2021).
rheumatoid arthritis (2 papers, 2014 to 2026). A chronic, systemic autoimmune disorder characterized by inflammation in the synovial membranes and articular surfaces. "In contrast, SFRP2 exhibits tissue‐specific roles, acting as an antifibrotic factor in rheumatoid arthritis (RA) while promoting fibrosis by enhancing collagen synthesis in human hypertrophic scars." (PMID 41541657, 2026).
scleroderma (2 papers, 2024 to 2025). Scleroderma is a rare autoimmune connective tissue disorder characterized by abnormal hardening of the skin and, sometimes, other organs. "Interferons (IFNs) have previously been reported to contribute to the transition of SFRP2+ fibroblasts to myofibroblasts in fibrosis, particularly in conditions like scleroderma." (PMID 40574847, 2025). "In scleroderma, where skin fibrosis is a predominant feature, activation of transcription factors driven by IFNs and TGF-β contribute to the transition of SFRP2+ fibroblasts to a myofibroblast phenotype." (PMID 38358820, 2024). "Our fibroblasts in NEOLP and EOLP shared transcriptional similarity with fibroblasts from skins of scleroderma patients (including CCL19+APOE+CXCL12+ fibroblasts and SFRP2+PRSS23+ fibroblasts), which indicated an overlap between inflammatory features of fibroblasts across OLP and other diseases." (PMID 40574847, 2025).
abnormal glucose tolerance (1 paper, 2016). An abnormal resistance to glucose, i.e., a reduction in the ability to maintain glucose levels in the blood stream within normal limits following oral or intravenous administration of glucose. "Circulating sFRP2 was higher in female patients and in those with abnormal glucose tolerance and correlated with increased age and BMI." (PMID 27685706, 2016). "In human subjects, circulating insulin levels positively correlated with serum sFRP2, and levels were higher in patients with abnormal glucose tolerance (34.2ng/ml) compared to controls (29.5ng/ml)." (PMID 27685706, 2016). "Unlike previous studies from a clinical setting, we measured circulating sFRP2 levels in serum from humans across a range of BMI and with normal and abnormal glucose tolerance and showed a positive correlation with serum insulin, triglyceride, HOMA%B and HOMAIR." (PMID 27685706, 2016).
adrenal adenomas (1 paper, 2021). "In accordance with this, Secreted Frizzled Related Protein 2 (SFRP2), a WNT inhibitor, was significantly downregulated in APAs compared to normal adrenal glands or non-functioning adrenal adenomas." (PMID 34771744, 2021).
Alzheimer disease (1 paper, 2023). A progressive, neurodegenerative disease characterized by loss of function and death of nerve cells in several areas of the brain leading to loss of cognitive function such as memory and language. "Studies have demonstrated a significant upregulation in the expression of Wnt signaling inhibitor proteins (such as DKK-1, SFRP-1, and SFRP-2) in postmortem AD brain and transgenic AD mouse models.This upregulation effectively suppresses the Wnt signaling pathway in Alzheimer's disease (AD)." (PMID 38041203, 2023).
bladder urothelial carcinoma (1 paper, 2022). "Moreover, we observed that both the SFRP1 and SFRP2 transcripts are significantly negatively correlated with tumor purity and positively correlated with CAF infiltration in bladder urothelial carcinoma, but the SFRP2 gene showed a more distinguished correlation." (PMID 35372028, 2022).
brachydactyly (1 paper, 2011). A disease characterized by the presence of brachydactyly, including syndromic and non-syndromic forms. "Inactivation of SFRP2 results in subtle limb defects in mice with mesomelic shortening and consistent shortening of all autopodal elements clinically manifested as brachydactyly." (PMID 21490961, 2011).
Cachexia (1 paper, 2019). Severe weight loss, wasting of muscle, loss of appetite, and general debility related to a chronic disease. "Against this background it is interesting to note that SFRP2 and −4 are significantly downregulated in SAT among gastrointestinal cancer patients with cachexia compared to weight stable patients." (PMID 30884788, 2019).
cholangiocarcinoma (1 paper, 2019). A carcinoma that arises from the intrahepatic biliary tree (intrahepatic cholangiocarcinoma) or from the junction, or adjacent to the junction, of the right and left hepatic ducts (hilar cholangiocarcinoma). "The activity of SFRP2, a Wnt signaling inhibitor, is silenced in cholangiocarcinoma because of the hypermethylation of its gene." (PMID 31684152, 2019). "The activation of Wnt signaling has been detected in cholangiocarcinoma, and the validated mutations identified so far are an inhibitory ring finger protein 43 (RNF43) mutation, overexpression of Wntless, and hypermethylation of secreted frizzled-related protein 2 (SFRP2)." (PMID 31684152, 2019).
chronic hepatitis (1 paper, 2014). An active inflammatory process affecting the liver for more than six months. "Theme of this study was to check the promoter hypermethylation of cancer related target genes (SFRP2 & DKK1) in HCV infected chronic hepatitis, liver cirrhosis and HCC patients and compare that with infection free normal livers." (PMID 24947038, 2014). "Chronic hepatitis tissue samples exhibited significantly higher levels of methylation as compared to normal controls (p = 0.0136 & 0.0084 for SFRP2 & DKK1 respectively, Mann–Whitney U test)." (PMID 24947038, 2014). "SFRP2 promoter methylation level was analyzed in liver biopsy samples obtained from HCV-positive patients suffering from chronic hepatitis (n = 15) or liver cirrhosis (n = 13), without any concomitant tumorous growth on their livers." (PMID 24947038, 2014).
chronic lymphocytic leukemia (1 paper, 2014). "In chronic lymphocytic leukemia (CLL), TSGs including DAPK1, SFRP1 or SFRP2 have been shown to be aberrantly methylated (hypermethylated)." (PMID 24559316, 2014).
colitis (1 paper, 2015). Inflammation of the colon. "Aberrant methylation of APC2 (adenomatousis polyposis coli 2), SFRP1 (secreted frizzled-related protein 1), and SFRP2 (secreted frizzled-related protein 2) is associated with the progression from colitis to neoplasia." (PMID 26101583, 2015).
delirium (1 paper, 2018). A disorder characterized by confusion; inattentiveness; disorientation; illusions; hallucinations; agitation; and in some instances autonomic nervous system overactivity. "Five proteins (CHI3L1, IL6, SFRP2, PMP2, and RTN4R) differed in serum in patients with postoperative delirium compared to baseline with corrected p < 0.01 and 11 at p < 0.05." (PMID 30367354, 2018).
gastric adenocarcinoma (1 paper, 2021). "In addition, the expression of SFRP2/3/4 was higher in gastric adenocarcinoma of NOS and diffuse type, and gastric intestinal adenocarcinoma of mucinous type." (PMID 34205081, 2021). "We found that the expression of SFRP2/3/4 was higher in gastric adenocarcinoma of not otherwise specified (NOS) and diffuse type, and gastric intestinal adenocarcinoma of mucinous type." (PMID 34205081, 2021).
gastric tumour (1 paper, 2007). "When compared to adjacent non-cancer tissues, SFRP2 was found to be significantly downregulated in primary gastric tumour specimens." (PMID 17848950, 2007).
hepatitis C virus infection (1 paper, 2021). A viral infection caused by the hepatitis C virus. "Hepatitis C virus infection is also associated with promoter hypermethylation of the WNT pathway inhibitors, Secreted Frizzled-related Protein 2 gene (SFRP2) and DKK1, leading to WNT/b-catenin activation." (PMID 34422814, 2021).
Hyperglycemia (1 paper, 2021). An increased concentration of glucose in the blood. "These beneficial effects of SFRP2 on mitochondria may play a role in hyperglycemia and hyperlipidemia-induced cardiac remodeling and dysfunction." (PMID 34790288, 2021).
infarction (1 paper, 2020). A localised pathological necrosis of tissue resulting from obstruction of the blood supply usually by a thrombus, an embolus, or vascular torsion. "It has been reported that AKT-modified BMSCs mediated pro-survival effects in vitro as well as the diminution of infarction areas and the restoration of cardiac function in MI rodent hearts via the secretion of SFRP2." (PMID 31918758, 2020).